HJURP (Holliday junction recognition protein)
Diseases named in the same sentence as HJURP in open-access papers (continued):
Sharing a sentence is not in itself a finding about the gene and the disease.
non-small cell lung carcinoma (5 papers, 2017 to 2025). A group of at least three distinct histological types of lung cancer, including non-small cell squamous cell carcinoma, adenocarcinoma, and large cell carcinoma. "Furthermore, the higher HJURP level could be associated with early-stage LC while lower ADAMTS8 level could be correlated with non-small cell lung cancer." (PMID 28410204, 2017). "Back in 2007, a novel gene, initially annotated as fetal liver-expressing gene 1 (hFLEG1) and later termed Holliday junction recognition protein (HJURP), was found to show a fold change expression greater than five in non-small cell lung cancer compared to normal tissue." (PMID 37025176, 2023).
ovarian carcinoma (5 papers, 2019 to 2025). A malignant neoplasm originating from the surface ovarian epithelium. "One possible explanation was that silencing HJURP aroused chromosomal instability and collapse of DNA damage repair, which might bring about ovarian cancer cells susceptible to DNA damage." (PMID 35173547, 2022). "Furthermore, high expression of HJURP is associated with poor prognosis in patients with colorectal and ovarian cancer and is an independent prognostic biomarker for those cancers." (PMID 34434213, 2021). "HJURP was over-expressed in majorities of malignancies including ovarian cancer according to GEPIA database." (PMID 35173547, 2022). "The percentage of over-expressed HJURP in ovarian cancer (55.13%, 86/156) was more than that in fallopian tube (29.73%, 22/74)." (PMID 35173547, 2022). "The mRNA and protein levels of HJURP were significantly higher in ovarian cancer than those in fallopian tube, performed by qRT-PCR and WB." (PMID 35173547, 2022). "Altogether, HJURP has the potential to be a novel target in combined therapy and has the significant prognostic value of ovarian cancer." (PMID 35173547, 2022). "Kaplan-Meier analysis indicated that high HJURP expression had a worse prognosis in ovarian cancer patients, evaluated by OS (P=0.043) and PFS (P=0.022)." (PMID 35173547, 2022). "In conclusion, our results indicated that HJURP was over-expressed and promoted malignant progression in ovarian cancer." (PMID 35173547, 2022). "Collectively, our data displays that HJURP promotes tumor progression and chemoresistance of ovarian cancer, and HJURP has potential to be a novel therapeutic target in the combined treatment with cisplatin and AZD1775 in ovarian cancer." (PMID 35173547, 2022). "In our study, we found HJURP was over-expressed in ovarian cancer and high expression of HJURP was correlated to unfavorable prognosis." (PMID 35173547, 2022). "Besides, the function of HJURP in proliferation and metastasis was explored in ovarian cancer both in vitro and in vivo." (PMID 35173547, 2022). "HJURP knockdown could inhibit proliferation, metastasis and induce G0/G1 stagnation of ovarian cancer cells." (PMID 35173547, 2022). "Interestingly, MYC was positively correlated with HJURP both in GEPIA ovarian cancer database and in 30 tumor specimens from our laboratory." (PMID 35173547, 2022). "All findings displayed that HJURP was over-expressed in ovarian cancer and correlated with poor prognosis, implying HJURP may play a key role in ovarian cancer progression." (PMID 35173547, 2022). "We found that silencing HJURP could enhance sensitivity of ovarian cancer cells to cisplatin and AZD1775." (PMID 35173547, 2022). "Collectively, silencing HJURP could enhance sensitivity of ovarian cancer cells to AZD1775, and HJURP probably affected cancer response to AZD1775 through mediation of DNA damage repair." (PMID 35173547, 2022). "In the present study, the expression and prognostic value of HJURP was detected in ovarian cancer." (PMID 35173547, 2022). "In addition, HJURP was positively correlated with WEE1 in ovarian cancer according to GEPIA database, and protein level of WEE1 after silencing HJURP was also detected by WB." (PMID 35173547, 2022). "Additionally, we investigated that silencing HJURP increased sensitivity of ovarian cancer cells to cisplatin via MYC/WEE1 axis, and HJURP participated in DNA repair of cisplatin-induced damage." (PMID 35173547, 2022). "Then, we found that HJURP knockdown could inhibit ovarian cancer proliferation both in vitro and in vivo." (PMID 35173547, 2022). "All parameters above were symbol of advanced or progressive phenomenon of ovarian cancer, indicating that HJURP may participate in the malignant progression." (PMID 35173547, 2022). "All results indicated that silencing HJURP could enhance sensitivity of ovarian cancer cells to cisplatin, and combined treatment of cisplatin and HJURP interference could provide a novel strategy against chemoresistance." (PMID 35173547, 2022).
ovarian carcinoma (continued). "More interestingly, silencing HJURP could enhance sensitivity of ovarian cancer cells to AZD1775 and improve the synergistic effect of cisplatin plus AZD1775 combined therapy." (PMID 35173547, 2022). "Besides, high expression of HJURP was a risk factor for PFS, and high HJURP level of tumor specimens correlated with poor prognosis in ovarian cancer patients." (PMID 35173547, 2022). "Moreover, HJURP was necessary for DNA repair of cisplatin-induced DNA damage, which might decrease sensitivity of ovarian cancer cells towards DNA damage agents." (PMID 35173547, 2022). "Furthermore, we found that silencing HJURP could modulate cisplatin sensitivity of ovarian cancer via MYC/WEE1 axis." (PMID 35173547, 2022). "Cisplatin treatment had an obvious efficacy on tumor growth inhibition, and shHJURP could enhance the inhibitory effect of cisplatin, which further confirmed the application of silencing HJURP for increasing sensitivity of ovarian cancer cells towards cisplatin." (PMID 35173547, 2022). "Collectively, HJURP could promote ovarian cancer progression, and all findings had provided foundation for subsequent studies about HJURP downstream-regulated networks and potential value of silencing HJURP in ovarian cancer therapy." (PMID 35173547, 2022). "However, the prognostic value of HJURP in ovarian cancer requires further verification, and the function of HJURP in ovarian cancer still remains unclear." (PMID 35173547, 2022). "In ovarian cancer, the CAF-derived Holliday Junction Recognition Protein (HJURP) enhances glutamine metabolism and tricarboxylic acid (TCA) cycle activity, facilitating resistance to doxorubicin." (PMID 40940809, 2025). "Eight genes (NUF2, GTSE1, DEPDC1, KIF18B, PBK, CEP55, HJURP, SKA1) were potential hub genes correlated to ovarian cancer progression." (PMID 35173547, 2022). "In the present study, HJURP was found to be up-regulated in ovarian cancer tissues and considered to be a hub gene among DEGs in NGS data of ovarian cancer versus fallopian tube." (PMID 35173547, 2022). "Our studies firstly illustrated the function of HJURP in malignant progression and cisplatin/AZD1775 sensitivity of ovarian cancer, indicating HJURP to be a potential target in combinatory therapeutic strategies." (PMID 35173547, 2022). "Of the 12 upregulated genes VEGFA, HJURP, CCNE2, and RAD51 were also upregulated in the tissue of ovarian cancer patients according to in silico microarray data (Oncomine)." (PMID 31319587, 2019). "Besides, HJURP was over-expressed in HEY, SKOV3 and A2780 ovarian cancer cell lines compared with Hosepic control cell line." (PMID 35173547, 2022). "Based on the evidence above, we speculated that silencing HJURP could be beneficial to cisplatin or AZD1775 treatment and combined therapy was potential to be a novel strategy for resistant ovarian cancer." (PMID 35173547, 2022). "However, the function of HJURP in ovarian cancer has not been elucidated." (PMID 35173547, 2022). "However, the detailed mechanism was not fully elucidated, and whether HJURP could modulate AZD1775 sensitivity was worthy of exploration in ovarian cancer." (PMID 35173547, 2022).
renal cell carcinoma (5 papers, 2022 to 2025). "Other studies reported that HJURP levels were significantly higher in cancerous than those in normal tissues in pancreatic, lung, breast, prostate, and renal cell cancer, and its high expression was liked with poor survival." (PMID 35884419, 2022). "Therefore, whether HJURP plays a pro- or anti-cancer role in renal cell carcinoma deserves further investigation." (PMID 37025176, 2023).
triple-negative breast carcinoma (5 papers, 2010 to 2025). An invasive breast carcinoma which is negative for expression of estrogen receptor (ER), progesterone receptor (PR), and human epidermal growth factor receptor 2 (HER2). "Triple negative breast cancer has distinct clinical and pathological features, and also has relatively poor prognosis and aggressive behavior, consistent with our finding that high HJURP expression is associated with a bad prognosis." (PMID 20211017, 2010). "In Subtype 4, we identified the upregulation of the HJURP gene, which is a marker for triple-negative breast cancer." (PMID 40004168, 2025). "We observed significantly increased HJURP expression levels in triple-negative breast cancer compared to other subtypes." (PMID 35459269, 2022). "Taken together, these findings provide insights into the transcriptional regulation axis of HJURP/YAP1/NDRG1 in triple-negative breast cancer progression and therapeutic response." (PMID 35459269, 2022). "Therefore, our research mainly focuses on exploring the progression of triple-negative breast cancer and determines the important role of the HJURP/YAP1/NDRG1 transcriptional regulation axis in triple-negative breast cancer." (PMID 35459269, 2022). "And HJURP/YAP1/NDRG1 axis could affect cell proliferation and chemotherapy sensitivity in triple-negative breast cancer." (PMID 35459269, 2022).
clear cell renal carcinoma (3 papers, 2022 to 2025). A malignant epithelial neoplasm of the kidney characterized by the presence of lipid-containing clear cells within a vascular network. "HJURP has also been associated with the TME in clear cell renal cancer." (PMID 35783358, 2022).
endometrial cancer (3 papers, 2023 to 2025). Primary or metastatic malignant neoplasm involving the endometrium (mucous membrane that lines the endometrial cavity). "Within this network, 100 DEGs were found, and three genes (BIRC5, CENPF, HJURP) overlapping with DEM targets were associated with worse overall survival in endometrial cancer." (PMID 39108650, 2024). "Regarding HJURP expression, increased HJURP mRNA expression in endometrial carcinoma specimens was linked to high tumor grade, disease recurrence, and worse patients’ OS." (PMID 37958340, 2023).
lung adenocarcinoma (3 papers, 2022 to 2024). A carcinoma that arises from the lung and is characterized by the presence of malignant glandular epithelial cells. "In this study, we identified Holliday Junction Recognition Protein (HJURP) as a significant prognostic biomarker for lung adenocarcinoma (LUAD)." (PMID 39649097, 2024).
oral squamous cell carcinoma (3 papers, 2024 to 2025). "Ferroptosis of oral squamous cell carcinoma was also restrained by Nrf1-target holiday junction recognition protein (HJURP), leading to the cancer progression." (PMID 40703332, 2025). "NFE2L1 restrains ferroptosis by transcriptionally regulating the Holliday junction recognition protein (HJURP) and participates in the progress of Oral Squamous Cell Carcinoma (OSCC)." (PMID 39061827, 2024). "For example, in human oral squamous cell carcinoma cells, NFE2L1 can increase ferroptosis resistance through the Holliday junction recognition protein (HJURP)." (PMID 39025451, 2024).
serous ovarian cancer (3 papers, 2019 to 2025). "Interestingly, HJURP is one of hub genes analyzed from top 30 differentially up-regulated genes in high-grade serous ovarian cancer versus fallopian tube according to our NGS data." (PMID 35173547, 2022). "Given previous evidence that HJURP promotes malignant progression and mediates cisplatin sensitivity via MYC in serous ovarian cancer, we focused on MYC for further investigation." (PMID 40290723, 2025).
astrocytoma (2 papers, 2013 to 2023). "Here we found that HJURP over expression in astrocytoma patients of our cohort is also associated with poor survival." (PMID 23638004, 2013). "We also observed that tumors presenting the higher expression levels of HJURP are associated with poor survival prognosis, indicating HJURP overexpression as an independent prognostic factor of death risk for astrocytoma patients." (PMID 23638004, 2013). "HJURP is highly expressed in low-grade diffuse (grade II) astrocytoma, anaplastic (grade III) astrocytoma, and glioblastoma (grade IV)." (PMID 37025176, 2023). "Median values of the relative expression of HJURP mRNA were 74 and 86 in astrocytomas of grade II and III, respectively." (PMID 23638004, 2013). "Here we show that HJURP is remarkably overexpressed in a cohort composed of 40 patients with different grade astrocytomas." (PMID 23638004, 2013). "Here we show that HJURP is also over expressed in low-grade diffuse (grade II) and anaplastic (grade III) astrocytomas." (PMID 23638004, 2013).
invasive ductal carcinoma (2 papers, 2010 to 2014). "Furthermore, HJURP mRNA expression in invasive ductal carcinoma (IDC) is significantly higher than that present in normal breast ducts." (PMID 25243117, 2014). "Furthermore, HJURP mRNA levels in invasive ductal carcinomas (IDC) were statistically significantly higher than its levels in the normal breast ducts (P < 0.0001)." (PMID 20211017, 2010).
oral cancer (2 papers, 2023). "Both DAXX and HJURP expression was reported upregulated in oral cancer tissue specimens compared to non-tumorous control samples, with HJURP overexpression exhibiting further association with patients’ age and shorter OS." (PMID 37958340, 2023).
thymic carcinoma (2 papers, 2022). Thymic carcinoma (TC) is a type of thymic epithelial neoplasm characterized by a high malignant potential. "Interestingly, both nuclear and cytoplasmic CENP-A, as well as cytoplasmic HJURP, were higher in B3 thymomas and thymic carcinomas." (PMID 35955489, 2022).
thymic epithelial tumor (2 papers, 2022 to 2023). "In thymic epithelial tumor (TET) patients, increased cytoplasmic HJURP expression associated with advanced Masaoka–Koga stage and its presence correlated with lymphocyte-poor TETs." (PMID 37958340, 2023).
Alpha-thalassemia (1 paper, 2023). Alpha-thalassemia is an inherited hemoglobinopathy characterized by impaired synthesis of alpha-globin chains leading to a variable clinical picture depending on the number of affected alleles. "We consider four key protein complexes: chromatin assembly factor 1 (CAF-1) complex, histone regulator A (HIRA) complex, death domain-associated and alpha-thalassemia/mental retardation, X-linked protein (DAXX/ATRX) complex, and Holliday junction recognition protein (HJURP) complex (top row)." (PMID 37734377, 2023).
anaplastic astrocytoma (1 paper, 2013). "The anaplastic astrocytomas revealed even higher quantities of HJURP mRNA." (PMID 23638004, 2013).
ataxia telangiectasia (1 paper, 2024). Ataxia-telangiectasia is the association of severe combined immunodeficiency (affecting mainly the humoral immune response) with progressive cerebellar ataxia. "HJURP is considered a potential downstream target of ataxia telangiectasia mutated signaling, and its expression is upregulated by DNA double-strand breaks (DSBs)." (PMID 39649097, 2024).
chronic lung disease (1 paper, 2018). According to the definitions of the American and British Thoracic Societies, including pulmonary functional tests, X-rays, and CT scans for items such as fibrosis, bronchiectasis, bullae, emphysema, nodular or lymphomatous abnormalities. "Based on the hypothesis on the origin of chronic lung diseases like COPD during the early life events, we could detect three novel (HJURP, MCRS1 and TLR8) COPD candidate genes and replicate the findings in 17 other studies using a mouse-human translational datamining approach." (PMID 29871630, 2018).
cutaneous melanoma (1 paper, 2021). A primary melanoma arising from atypical melanocytes in the skin. "Our results revealed several novel biomarkers and biological pathways that participate in the pathogenesis of cutaneous melanoma, and demonstrated the diagnostic and prognostic value of CDC45, CENPF, DTL, FANCI, GINS2, HJURP, TPX2 and TRIP13." (PMID 33531976, 2021).
kidney cancer (1 paper, 2023). Primary or metastatic malignant neoplasm involving the kidney. "It was further shown that HJURP induces apoptosis in kidney cancer cells by promoting ROS accumulation through inactivation of PPARγ/SIRT1 and downstream Forkhead box O3 (FOXO3a) signaling." (PMID 37025176, 2023). "When overexpressed, HJURP was found to inhibit the proliferation of A498 kidney cancer cells, induce an increase in apoptosis, and block the cell cycle at the G0/G1 phase." (PMID 37025176, 2023). "Overexpression of HJURP and clinicopathological features of kidney cancer patients, such as T-stage, N-stage, M-stage, clinical stage, and pathological grade, were significantly correlated." (PMID 37025176, 2023). "Analysis of tumor mRNA expression profiles in the TCGA database revealed that the expression of HJURP was higher in kidney cancer than in normal adjacent tissues." (PMID 37025176, 2023). "This evidence suggested that HJURP may promote the invasive migration of kidney cancer cells through the AKT signaling pathway." (PMID 37025176, 2023).
liver fibrosis (1 paper, 2022). "Among HJURP-related module eigengenes, MEcyan and MEgreenyellow were found to be associated with TME signatures, and their expression correlated positively with hepatic tissue inflammation and liver fibrosis (p < 0.01)." (PMID 35783358, 2022).
lymph node metastasis (1 paper, 2024). "However, in non-lymph node metastasis patients, high HJURP expression was associated with poor overall survival." (PMID 39139392, 2024). "HJURP expression was associated with shorter overall survival in lymph node metastasis plus estrogen receptor-positive or human epidermal growth factor receptor-2-positive BCa group, but not with TNBC, which might be due to the limited number of patients in this group." (PMID 39139392, 2024). "Although patients with high HJURP expression had worse overall survival than the lower expression group in lymph node metastasis BCa patients, no statistical difference was observed." (PMID 39139392, 2024).
metastatic melanoma (1 paper, 2023). A melanoma that has spread from its primary site to another anatomic site. "Among the top 5 candidate genes (UBE2C, ASF1B, FOXM1, HJURP, and KIF18B), UBE2C was the most frequently associated with poor prognosis in publicly available clinical datasets from diverse cancer types, including metastatic melanoma." (PMID 37215954, 2023).
ovarian serous cystadenocarcinoma (1 paper, 2023). A malignant serous cystic epithelial neoplasm arising from the ovary. "A recent study revealed that mRNA and protein levels of HJURP in Ovarian serous cystadenocarcinoma (OV) tissues were significantly higher than those detected in normal fallopian tube; consistently, HJURP was also overexpressed in OV cell lines compared to normal ovarian epithelial cells." (PMID 37025176, 2023).